CCL7 (C-C motif chemokine ligand 7)
Diseases named in the same sentence as CCL7 in open-access papers (continued):
Sharing a sentence is not in itself a finding about the gene and the disease.
oral squamous cell carcinoma (5 papers, 2014 to 2021). "CCL7 derived from cancer-associated fibroblasts stimulated the migration and invasion of oral squamous cell carcinoma and liver cancer." (PMID 34206004, 2021). "For example, CCL7 was reported to be upregulated in cancer-associated fibroblasts (CAFs) cultured with oral squamous cell carcinoma (OSCC) cells and potentiated tumor migration and invasion in vitro." (PMID 30764543, 2019). "Oral squamous cell carcinoma (OSCC)-derived CAFs secrete CCL7 to up-regulate MMP2 expression by OSCC cells and thus increase cancer invasion." (PMID 26954362, 2016). "CCL7 promotes the invasion and migration of oral squamous cell carcinoma cells through directly binding to its receptor." (PMID 25193015, 2014).
tuberculosis (5 papers, 2009 to 2026). A chronic, recurrent infection caused by the bacterium Mycobacterium tuberculosis. "In parallel, the monocyte-attracting chemokines CCL2, CCL8, and CCL7, associated with septic shock and tuberculosis, were elevated supporting the role of monocytes in disease pathogenesis." (PMID 33239683, 2020). "MCP-3 (CCL7) recruits immune cells for protective immunity and has potential utility in differentiating LTBI from active tuberculosis, particularly in immunocompromised populations." (PMID 41488476, 2025).
Arthritis (4 papers, 2005 to 2024). Inflammation of a joint. "The 1,407 genes with increased expression in DA and reciprocally decreased expression in DA.F344(Cia5a) congenics included pro-inflammatory cytokines and chemokines implicated in arthritis pathogenesis such as Il1b (5.17-fold on microarray, and 2.46-fold on qPCR), Il18, Mif, Ccl2, Ccl7 and Cxcl13." (PMID 23249408, 2012). "However, most early arthritis genes in clusters C and D showed an expression peak later, at the acute phase of inflammation, and encoded chemokine receptors (Ccr2 and Ccr5) and chemokine ligands (Cxcl1, Ccl2, Ccl7, and Ccl9)." (PMID 15743466, 2005). "This was also supported by work from a different group who first identified CCL7 in RA tissue and found it to be ‘abundantly present’ in all arthritis and control groups tested." (PMID 28648867, 2017).
heart failure (4 papers, 2021 to 2025). Inability of the heart to pump blood at an adequate rate to meet tissue metabolic requirements. "Transcript levels of several established biomarkers, including Spp1, Sfrp1, Sfrp2, Tnc, Vim, Mmp9, and Tnfrsf1a, and several inflammatory markers that are known to be activated in heart failure, such as Cd44, Cd83, Ccl7, Irf7, and Nr4a2, were upregulated in the Myh6-McmTamDspfl/fl cardiomyocytes." (PMID 40608429, 2025). "Although there was an apparent association between CCL7 and LV ejection fraction (%), this finding was driven by the two patients with severe heart failure (data not shown)." (PMID 39073768, 2024).
injury (4 papers, 2013 to 2024). Damage inflicted on the body as the direct or indirect result of an external force, with or without disruption of structural continuity. "Furthermore, a recent study reported that other chemokines, including CCL7 and CCL9, were elevated during APAP-induced liver injury, which is consistent with our results." (PMID 39363292, 2024). "In addition, CCL2, CCL7, and CCL12 have been found in areas of the brain after traumatic brain injury." (PMID 35820932, 2022).
Insulin resistance (4 papers, 2016 to 2024). Increased resistance towards insulin, that is, diminished effectiveness of insulin in reducing blood glucose levels. "It is posited that CCL7 may play a role in the onset of adipose tissue inflammation and insulin resistance in T2D and could be linked to the advancement of inflammation and fibrosis in DN." (PMID 39040677, 2024). "Interestingly, in mice with severe combined immunodeficiency on a normal chow diet, insulin resistance was associated with increased CCL7 levels." (PMID 36109744, 2022). "Recent findings have illustrated that CCL7 levels correlate with the degree of insulin resistance and the presence of metabolic syndrome in women with PCOS." (PMID 39691364, 2024). "Altogether, CCL7 may be involved in the development of adipocyte inflammation and insulin resistance in type 2 DM." (PMID 36109744, 2022). "Furthermore, increased CCL7 expression in the adipose tissue of obese and type 2 diabetic individuals correlates with macrophage infiltration and systemic inflammation, underscoring its importance in inflammation and insulin resistance in these conditions." (PMID 39691364, 2024). "In summary, our study found that CCL7 levels are elevated in the secretory phase endometrium of PCOS patients, suggesting that it plays a key role in exacerbating chronic inflammation, insulin resistance, ovarian dysfunction, and endometrial dysfunction." (PMID 39691364, 2024). "This connection implies that CCL7 may serve as a critical link between inflammation and the metabolic features of PCOS, where elevated levels could exacerbate insulin resistance, thus further complicating the clinical picture of the disease." (PMID 39691364, 2024).
kidney stone (4 papers, 2021 to 2024). "Among 92 patients with kidney stone who underwent percutaneous nephrolithotomy, CCL7 expression was markedly enhanced in the papillary tips versus urine samples." (PMID 38235001, 2023). "CCL7 expression is markedly enhanced in the papillary tips, kidney urine, and bladder urine of patients with nephrolithiasis." (PMID 36109744, 2022). "Previous studies have shown the relationships between CCL7 and kidney damage in different models of kidney diseases, such as kidney injury, glomerulonephritis, kidney stone, end-stage renal disease and so on." (PMID 36109744, 2022). "CCL7 gene plays a key biological function in both CaOx and CaP kidney stones, indicating that CCL7 may play a critical role in the development of calcium crystals." (PMID 38235001, 2023). "Moreover, the elevated expression of ceRNAs such as NEAT1, PVT1, hsa-miR-23b-3p, hsa-miR-429, hsa-miR-139-5p, CCL7, and ROBO2, along with the presence of infiltrating immune cells like Mps and mast cells, may be associated with the development of kidney stones." (PMID 38397450, 2024). "The results indicated that significant expressions of ceRNAs (NEAT1, PVT1, hsa-miR23b-3p, hsa-miR-429, hsa-miR-139-5p, CCL7, and ROBO2) and infiltrating immune cells (Mps and mast cells) may be involved in the pathogenesis of kidney stones." (PMID 38397450, 2024).
lung adenoma (4 papers, 2018 to 2022). A benign, well circumscribed epithelial neoplasm that arises from the bronchus or the lung parenchyma. "According to previous studies, higher CCL7 expression has been identified in metastatic renal cell carcinoma than in primary renal cell carcinoma and is upregulated in lung adenomas, which show marker accumulation of immune cells." (PMID 33175885, 2020). "CCL7 is upregulated in lung adenomas isolated from old mice, which show marked accumulation of immune cells, and lung adenomas formed on an aging background are more invasive." (PMID 29915688, 2018).
non-small cell lung carcinoma (4 papers, 2018 to 2024). A group of at least three distinct histological types of lung cancer, including non-small cell squamous cell carcinoma, adenocarcinoma, and large cell carcinoma. "In addition, increased expression of CCL7 was associated with higher incidence of bone metastasis of non-small cell lung cancer cells." (PMID 35715847, 2022). "Non-small cell lung carcinoma (NSCLC) activates the ROS/PI3K/AKT axis, releases cytokines such as VEGF-C, CCL7, and IL-8 to recruit macrophages, and upregulates M-CSF expression to drive M2 polarization, thereby facilitating NSCLC progression." (PMID 39430253, 2024).
pancreatic ductal adenocarcinoma (4 papers, 2020 to 2022). An infiltrating adenocarcinoma that arises from the epithelial cells of the pancreas. "For example, it has been demonstrated that oncolytic parvovirus can facilitate the recruitment of NK cells by expressing cytokines IL-2 and MCP-3/CCL7 in a pancreatic ductal adenocarcinoma model." (PMID 33680911, 2020). "Indeed, similar to our observations in the CCL7 3'UTR, a variant closely located to a miR-199a binding site at the 3'UTR of the HIF1A gene, is associated with pancreatic ductal adenocarcinoma risk and worse clinical outcomes." (PMID 35711383, 2022). "For example, MCP3/CCL7, IL4 and IL3 have been previously shown to be involved in the tumour microenvironment of pancreatic ductal adenocarcinoma and play a complex role in the regulation of tumour-promoting inflammation." (PMID 35064782, 2022).
renal carcinoma (4 papers, 2019 to 2026). A carcinoma arising from the epithelium of the renal parenchyma or the renal pelvis. "Evidence suggests that enhanced expression of CCL7 can promote cell growth and metastasis in renal cancer." (PMID 37679715, 2023). "This study aimed to evaluate the usefulness of the C-C motif chemokine ligand 3 (CCL3) and C-C motif chemokine ligand 7 (CCL7) by assessing their serum concentrations in 40 patients with stage G1 + G2 and stage G3 + G4 renal cancer, as well as in 58 healthy volunteers." (PMID 41828706, 2026).
renal cell carcinoma (4 papers, 2014 to 2020). "In the signature, CCL7 increased the peripheral blood mononuclear cell recruitment in renal cell cancer through the inhibition of let-7d." (PMID 33194402, 2020). "Even brain cancer metastases were shown to carry a higher expression of CCL7 compared with primary tumors of renal cell cancer (RCC)." (PMID 30764543, 2019).
type 1 diabetes (4 papers, 2015 to 2024). "Studies show that in type 1 diabetes, CCL7 contributes to immune cells, aggravating β-cell destruction." (PMID 39691364, 2024). "CCL7 was previously called monocyte-chemotactic protein-3 (MCP-3), which could be up-regulated in early renal injury in adolescent patients with type 1 diabetes." (PMID 32365893, 2020).
Allergy (3 papers, 2012 to 2021). An allergy is an immune response or reaction to substances that are usually not harmful. "RASD2, IL24, CCL2 and CCL7 are immunologically relevant biomarkers in allergy." (PMID 33849432, 2021). "In allergic conjunctivitis, Ccl7 promotes FcεRI-mediated allergic reaction." (PMID 34093515, 2021). "Therefore, Ccl7 and Cxcl10 are potential targets to overcome allergic diseases." (PMID 34093515, 2021). "While both CCL5 and CCL7/MCP-3 are able to activate and to induce the chemotaxis of eosinophil and basophil granulocytes in allergy, CCL11/Eotaxin has been found to be a powerful attractant for eosinophils and has also been identified in atherosclerotic lesions." (PMID 22807925, 2012).
Granuloma (3 papers, 2010 to 2022). A compact, organized collection of mature mononuclear phagocytes, which may be but is not necessarily accompanied by accessory features such as necrosis. "Additionally, we demonstrate that CCL7 immunolocalises to the fibrotic zone of granulomas." (PMID 20161726, 2010). "Expression of the chemokines CCL21, CXCL1, CCL7 and CCL12 showed a significant correlation with the expression of procollagen genes and resembled the recruitment of HSCs into granulomas." (PMID 20161726, 2010). "Up-regulation of CCL6, CCL7 and CCL8 has previously been reported for S. mansoni infection and so might represent a common mechanism whereby macrophages are recruited into schistosome-induced granulomas." (PMID 20161726, 2010).
HIV-1 infection (3 papers, 2017 to 2023). The type species of lentivirus and the etiologic agent of acquired immunodeficiency syndrome (AIDS). "The affinity of CCL3L1 binding to CCR5 was much higher than that to CCL3 and CCL5, and CCL3L1 is the most potent agonist of CCR5 and suppresses HIV-1 infection, whereas CCL7/MCP-3 is the main antagonistic ligand of CCR5." (PMID 37198402, 2023). "CCL7, CCL2, CCL3 and others are overexpressed during HIV-1 infection, contributing to the secretion of more pro-inflammatory cytokines, leading to chronicity of the infectious process observed in HIV-positive individuals." (PMID 33557210, 2021).
Hyperglycemia (3 papers, 2014 to 2023). An increased concentration of glucose in the blood. "Limited clinical data suggest that acute hyperglycemia may cause upregulated urinary CCL7 expression in patients with type 1 DM." (PMID 36109744, 2022). "Acute hyperglycemia can result in upregulated urinary expression of CCL7 in patients with type 1 DM." (PMID 36109744, 2022). "Taken together, we suggest that the decreased expression of CCL7 by MC38 cells induced by hyperglycemia resulted in reduced tumor infiltration of DCs, resulting in limited CD8+ T cell tumor infiltration due to a lack of cancer antigen presentation by DCs in the dLNs." (PMID 37046033, 2023).
ischemic stroke (3 papers, 2018 to 2022). A stroke disorder caused by obstruction of blood flow to the brain, due to thrombotic (local blood clot formation) or embolic (due to a blood clot or other material traveling from another site) event. "Ischemic stroke induces the release of different chemokines such as CCL-2, CCL-3, CCL-4, CCL7, CCL-11, CXCL-1, CXCL10, from the ischemic tissue." (PMID 30584250, 2018).
liver cancer (3 papers, 2021 to 2025). An epithelial or non-epithelial malignant neoplasm that arises from the liver. "However, liver cancer cells exhibit a limited capacity to secrete CCL7." (PMID 40062588, 2025). "Together with CCL7, CCL5 activates chemokine receptor 1 (CCR1), which was found to promote liver cancer by inducing myeloid cell infiltration and angiogenesis." (PMID 35585513, 2022).
lupus (3 papers, 2021 to 2022). "Furthermore, CTSS-overexpressing mice showed a marked increase in the production of IL-17, TNF-α, IFN-α and IFN-γ, which are known to be associated with lupus development, and the chemoattractants CCL2, CCL7 and CCLl12, which are activated by IFN-α to attract monocytes to inflammatory sites." (PMID 34381063, 2021).
malaria (3 papers, 2013 to 2023). Malaria is a serious and sometimes fatal disease caused by a parasite that commonly infects a certain type of mosquito which feeds on humans. "The systemic presence of CCL2 and CCL7 in malaria, mainly at early time points in infection, was critically dependent on intact IFN-γ signaling and not affected by the absence of TLR-signalling." (PMID 23762028, 2013). "In malaria, both CXCL10 and CCL2 serum protein levels increased reaching peak levels between day 4 and 7 after infection whereas CCL7 was constitutively deregulated in Ccr2-deficient animals." (PMID 23762028, 2013). "In this malaria model, IFN-γ signalling and concurrent secretion of C-C motif ligand 2/7 (CCL2/CCL7) chemokines by BM stromal cells seem required for HSPC mobilization." (PMID 26903708, 2016).
metabolic syndrome (3 papers, 2024 to 2026). A cluster of metabolic risk factors for CARDIOVASCULAR DISEASES and TYPE 2 DIABETES MELLITUS. "Altered levels of distinct chemokines, like CCL5/RANTES, CXCL12/SDF-1a, CCL7/MCP-3, CCL2/MCP-1, CXCL1/GROa, and the eotaxin family, contribute to the development and/or exacerbation of inflammation, which is a common feature of numerous skin diseases as well as metabolic syndrome." (PMID 42042898, 2026).
multiple sclerosis (3 papers, 2005 to 2024). A progressive autoimmune disorder affecting the central nervous system resulting in demyelination. "Complementing the genetic associations, we also detected a distinct regional expression regulation for CCL2, CCL7 and CCL8 in correlation with chronic inflammation in multiple sclerosis brains." (PMID 15730561, 2005).
oral carcinoma (3 papers, 2015 to 2025). "For example, IL-1α secreted from oral carcinoma cells (OSCC) was shown to induce chemokine (C–C motif) ligand 7 (CCL7) release from oral CAF, which in turn promoted OSCC invasion." (PMID 41392310, 2025). "Similarly, a CCL7 neutralizing antibody has been shown to inhibit CCL7-induced invasion and migration of oral carcinoma cells, and anti-CCL2 and-CCR3 antibodies are also being evaluated." (PMID 26046767, 2015).
peritonitis (3 papers, 2013 to 2020). Inflammation of the peritoneum (tissue that lines the abdominal wall and covers most of the organs in the abdomen). "The Cxcl13+ FALC cover cell cluster was distinguished by the expression of the monocyte chemoattractants Ccl2 and Ccl7 and the neutrophil chemoattractants Cxcl1 and Cxcl10, suggesting a role for these cells in orchestrating the recruitment of inflammatory cells during peritonitis." (PMID 32294409, 2020). "Several studies indicate that Ccl2 and Ccl7 are the primary agonists of Ccr2, in which ablation of either of these ligands reduced monocyte recruitment from bone marrow to peripheral vessels in thioglycollate-induced peritonitis and Listeria monocytogenes infection." (PMID 25595590, 2015).
schizophrenia (3 papers, 2015 to 2024). A major psychotic disorder characterized by abnormalities in the perception or expression of reality. "Some earlier reports support an association of CXCL1 and CCL7 with psychotic disorders, although in previous reports their serum level or gene expression has been elevated in patients with schizophrenia." (PMID 25970596, 2015). "We identified seven inflammation markers linked to schizophrenia onset, which all passed the Bonferroni correction for multiple comparisons (bNGF, GROA(CXCL1), IL-8, M-CSF, MCP-3 (CCL7), TNF-β, CRP)." (PMID 38445386, 2024).
thyroid cancer (3 papers, 2016 to 2021). "We tested the mRNA levels of six more genes, including three with different abundance in antibody array between FTC and FA, two previously reported TAMs recruiters (CCL2 and CCL7), and CSF-1 which was reported as TAMs recruiters in thyroid cancers." (PMID 26875556, 2016). "CCL2 is overexpressed in liver, breast, gastric, and thyroid cancer 11; CCL5 is overexpressed in gastric, pancreatic, breast, colorectal, prostate, liver, and thyroid cancer 12; CCL7 is markedly upregulated in lung, gastric, colorectal, and uroepithelial cancer." (PMID 33123272, 2020). "Mice were treated with doxycycline for one week to develop thyroid cancer, and the expression levels of CCL2, CSF-1, LGALS3BP, INPP5D and CCL7, together with that of the chemokine receptors CCR2 and CSF1R, were measured in cancer specimens by quantitative RT-PCR." (PMID 34299284, 2021).
abdominal aortic aneurysm (2 papers, 2021 to 2022). Enlargement and ballooning of the vessel that supplies arterial blood to the abdomen, pelvis and legs. "CCL7 leads to angiotensin-II-induced abdominal aortic aneurysm by promoting the M1 phenotype of macrophages through the CCR1/JAK2/STAT1 signaling pathway." (PMID 36109744, 2022).
adenoma (2 papers, 2021 to 2022). A neoplasm arising from the epithelium. "Both the fold change in expression of CCL2, CCL7, and CCL8 and gene expression in adenoma were inversely correlated with a cumulative risk of transformation." (PMID 34884259, 2021). "In the case of CCL7, its expression concomitantly decreased in adenoma and increased in macroscopically normal tissue." (PMID 34884259, 2021). "CCL2, CCL7 and CCL8 expression tended to decrease in the polyps compared with the normal tissue, though more markedly in the case of adenomas with high-grade dysplasia." (PMID 34884259, 2021). "CCL2, CCL7, and CCL8 expression was the highest in the hyperplastic polyps and lower in the adenomas, in which it gradually decreased along with an increasing villous component." (PMID 34884259, 2021). "A stepwise method was applied to co-analyze the effect of the dysplasia grade, adenoma growth pattern, adenoma size, number of polyps, and subsite and patient’s age and sex on CCL2, CCL7, and CCL7 expression in colorectal adenomas." (PMID 34884259, 2021). "The fold change in CCL2, CCL7, and CCL8 expression decreased gradually along with an increasing villous component in the adenomas." (PMID 34884259, 2021).